KATNB1 (katanin regulatory subunit B1)
Description:
Participates in a complex which severs microtubules in an ATP-dependent manner. May act to target the enzymatic subunit of this complex to sites of action such as the centrosome. Microtubule severing may promote rapid reorganization of cellular microtubule arrays and the release of microtubules from the centrosome following nucleation. Microtubule release from the mitotic spindle poles may allow depolymerization of the microtubule end proximal to the spindle pole, leading to poleward microtubule flux and poleward motion of chromosome. Microtubule release within the cell body of neurons may be required for their transport into neuronal processes by microtubule-dependent motor proteins. This transport is required for axonal growth.
Synonyms: KAT; LIS6
Tractability: Antibody: its Gene Ontology location is reachable by antibodies, with high confidence. PROTAC: ubiquitination databases record sites on it; its protein half-life has been measured.
Target class: Other cytosolic protein
Gene: Protein-coding gene on chromosome 16 (57,735,669 to 57,758,271, forward strand). Ensembl gene ENSG00000140854.
Subcellular location: Cytoplasm; Cytoplasm, cytoskeleton, microtubule organizing center, centrosome; Cytoplasm, cytoskeleton, spindle pole; Cytoplasm, cytoskeleton; Cytoplasm, cytoskeleton, spindle
Subcellular location (Human Protein Atlas): Cytosol; Microtubules; Plasma membrane
Gene Ontology:
Molecular function: ATPase regulator activity; protein binding; protein heterodimerization activity; microtubule binding; dynein complex binding
Biological process: negative regulation of microtubule depolymerization; positive regulation of microtubule depolymerization; cytoplasmic microtubule organization; microtubule depolymerization; protein targeting; microtubule severing; mitotic chromosome movement towards spindle pole; positive regulation of apoptotic process; positive regulation of neuron projection development
Cellular component: cytoplasm; cytosol; katanin complex; membrane; microtubule; microtubule cytoskeleton; nucleus; spindle; spindle pole; axon; centrosome; cytoskeleton; growth cone; microtubule organizing center; midbody; neuronal cell body
Genetic constraint (gnomAD): Loss-of-function variants: 38 observed, 76.46 expected, observed/expected ratio (o/e) 0.5, 90% interval 0.38 to 0.65. The upper end of that interval is the gene's LOEUF score, 0.65, which puts it in group 2 of 6, group 1 being the genes least tolerant of losing a copy. Missense variants: 749 observed, 895.24 expected, observed/expected ratio (o/e) 0.84, 90% interval 0.79 to 0.89. Synonymous variants: 361 observed, 364.06 expected, observed/expected ratio (o/e) 0.99, 90% interval 0.91 to 1.08.
Homologues: Orthologues: chimpanzee KATNB1 (99% identical), macaque KATNB1 (99% identical), rabbit KATNB1 (97% identical), dog KATNB1 (96% identical), mouse Katnb1 (96% identical), guinea pig KATNB1 (95% identical), rat Katnb1 (95% identical), pig KATNB1 (89% identical), tropical clawed frog katnb1 (75% identical), zebrafish katnb1 (66% identical), Drosophila melanogaster kat80 (33% identical), Caenorhabditis elegans F47G4.4 (24% identical), and 1 more.
Diseases named in the same sentence as KATNB1 in open-access papers:
KATNB1 is named in the same sentence as 26 diseases in open-access papers, as found by Europe PMC text mining. Sharing a sentence is not in itself a finding about the gene and the disease. The quoted sentences say what the papers report.
microcephaly (4 papers, 2017 to 2022). A congenital or acquired developmental disorder in which the circumference of the head is smaller than normal for the person's age and sex. "A multigene panel for brain malformations and microcephaly identified the homozygous splicing variant NM_005886.3:c.1416+1del in the KATNB1 gene in the older sister." (PMID 34202629, 2021). "An NGS panel including 83 genes associated with brain malformations and microcephaly showed an homozygous splice site variant in KATNB1: NM_005886.3:c.[1416 + 1del]; [1416 + 1del]." (PMID 34202629, 2021). "Human mutations in KATNB1 (p80) cause severe congenital cortical malformations, which encompass the clinical features of both microcephaly and lissencephaly." (PMID 28079116, 2017). "In case 1, primary microcephaly and brain malformations, including in particular nodular heterotopia, severe short stature and syndactyly, are perfectly compatible with the homozygous KATNB1 mutation we detected." (PMID 34202629, 2021).
infertile (3 papers, 2012 to 2022). "Genetic alternations of Katnb1 were observed in infertile men with oligoasthenoteratozoospermia." (PMID 26771610, 2016).
microlissencephaly (2 papers, 2015 to 2022). Microlissencephaly describes a heterogenous group of a rare cortical malformations characterized by lissencephaly in combination with severe congenital microcephaly, presenting with spasticity, severe developmental delay, and seizures and with survival varying from days to years. "p60 and p80 katanins regulate ciliogenesis and MT central pair formation in protists, whereas in mammalian cells, KATNB1 (p80) inhibits ciliogenesis and is mutated in patients with microlissencephaly, which is a ciliopathy-related condition." (PMID 26714646, 2015).
oligoasthenoteratozoospermia (2 papers, 2016 to 2022). A form of male infertility that is characterized by a combination of low number or oligozoospermia, poor motility or asthenozoospermia, and abnormal shape or teratozoospermia of sperms. "The KATNB1 (Katanin Regulatory Subunit B1) gene encodes the protein p80, and a missense mutation of this gene causes male infertility in mice characterized by oligoasthenoteratozoospermia and virtual absence of progressive motility." (PMID 35286314, 2022).
scoliosis (2 papers, 2022 to 2024). A congenital or acquired spinal deformity characterized by lateral curvature of the spine. "We demonstrate that Katnb1 function in foxj1a-positive motile-ciliated lineages is necessary for normal spine development and when deficient, leads to scoliosis." (PMID 36105588, 2022). "We define essential roles for Katnb1 in motile ciliated lineages, uncouple EC cilia and RF formation defects from spinal curvature, and identify abnormal CSF flow and cell stress responses as shared pathogenic signatures associated with scoliosis across diverse zebrafish models." (PMID 36105588, 2022). "To determine whether scoliosis specifically results from motile cilia dysfunction, we attempted to suppress spinal curvature in katnb1mh102/mh102 mutants via transgenic re-introduction of wild-type Katnb1 in foxj1a-positive motile-ciliated cell lineages (as described in)." (PMID 36105588, 2022).
Ataxia (1 paper, 2022). Ataxia refers to impaired coordination of voluntary muscle movement. "Interestingly, mutations in the ATL1, SPAST, RAB7A or KATNB1 genes have been previously associated with diseases presenting with hyperreflexia, sensory axonal neuropathy or sensory impairment among other signs, which overlap with clinical signs identified in this new ataxia subtype in our family." (PMID 35310830, 2022).
childhood absence epilepsy (1 paper, 2017). A familial generalized pediatric epilepsy, characterized by very frequent (multiple per day) absence seizures, usually occurring in children between the ages of 4 and 10 years, with, in most cases, a good prognosis. "CACNG3 is involved in Childhood Absence Epilepsy and is also associated with some cases of ASD while mutations of KATNB1 cause complex cerebral malformations." (PMID 28993790, 2017).
lung carcinoma (1 paper, 2023). "A signaling pathway of MALAT1/miR-328/KATNB1 was established to explain the down-regulation of KATNB1 mRNA in patients carrying haplotype GGGT and reduced lymph node size in lung cancer and tumor size in brain metastatic lung cancer." (PMID 36934373, 2023). "A signaling pathway of MALAT1/miR-328/KATNB1 was established in our study, which explained the down-regulated KATNB1 mRNA and katanin P80 levels in patients carrying haplotype GGGT and reduced lymph node size in lung cancer and tumor size in brain metastatic lung cancer." (PMID 36934373, 2023).
lymph node metastasis (1 paper, 2021). "Elevated KATNB1 expression is associated with larger tumor size, lymph node metastasis, advanced cancer staging (TNM), and decreased rate of disease-free (DFS) and overall patient (OS) survival." (PMID 34414183, 2021). "Elevated KATNB1 expression positively correlates with lymph node metastasis and advanced cancer staging (pN and TNM stages) and reduced overall survival (OS)." (PMID 34414183, 2021).
Primary microcephaly (1 paper, 2015). Head circumference below 2 standard deviations below the mean for age and gender at birth. "Recently, a centrosome-localised katanin p80 protein (KATNB1) associated with MT severing and mutated in primary microcephaly was shown to negatively regulate centriole and motile cilium formation." (PMID 26714646, 2015).
tumor (2 papers, 2014 to 2021). "We found KATNB1 down-regulated in our analysis and down-regulation of KATNB1 would decrease its ability to disassemble microtubules, thereby keeping tumor cells alive." (PMID 24871302, 2014). "KATNB1 mainly participates in the disassembly of microtubules, and it may be involved in tumor development." (PMID 24871302, 2014).
KATNB1 also shares sentences with these, for which no sentence is quoted: brain malformations (2 papers); Lissencephaly (2); Alzheimer disease (1); autosomal recessive primary microcephaly (1); cancer (1); ciliopathy (1); double cortex syndrome (1); heterotopia (1); Hyperreflexia (1); Intellectual disability (1); male infertility (1); Miller-Dieker syndrome (1); Sensory axonal neuropathy (1); sensory impairment (1); Spastic paraplegia (1).